CXCL12 (C-X-C motif chemokine ligand 12)
Diseases named in the same sentence as CXCL12 in open-access papers (continued):
Sharing a sentence is not in itself a finding about the gene and the disease.
tumor (continued). "The CXCL12/CXCR4 axis, together with a variety of other factors, regulated tumor growth and metastasis in OC and the concomitant expression of CD40 and CXCR4 in OC was strongly associated with pelvic metastasis." (PMID 36642706, 2023). "Mesenchymal cells and fibroblasts in tumor tissue secrete fibroblast growth factor (FGF), chemokine (C-X-C Motif) ligand 12 (CXCL12), and matrix metallopeptidase 2 (MMP2) to enhance tumor cell growth, invasion, and metastasis." (PMID 36909170, 2023). "The upregulation of tumor-promoting factors CC-chemokine ligand 5 (CCL5) and C-X-C motif chemokine ligand 12 (CXCL12) was efficiently blocked by BAMBI." (PMID 36834884, 2023). "An analysis of the AS events of CXCL12 and CXCR4 transcripts between multiple tumor and normal tissues suggested divergent expression of CCL12- or CXCR4-SVs in tumor tissues." (PMID 37198402, 2023). "Researchers introduced multiple CXCL12/CXCR4 inhibitors and antagonists to observe its effect on tumor development." (PMID 38313431, 2023). "Of the 11 neoplasm-related genes in these subclusters, the expression of six (ANGPT2, TP73, NOVA1, CDH11, CXCL12, and LAMA1) were significantly repressed in KRT and one (EPHA2) was higher expressed in KRT compared with IMU." (PMID 37654626, 2023). "It has also been shown that pMSC overexpress several proteins involved in the promotion of tumor angiogenesis, including CSPG4/NG2, CRYAB, CNN1, CALD1, and VASP, and secrete high levels of angiogenic factors such as SDF-1/CXCL12 and HGF." (PMID 37355636, 2023). "The receptors known for CXCL12 are CXCR4 and CXCR7 and are expressed by tumor cells and a range of other cells, such as immune cells, fibroblasts, and endothelial cells." (PMID 38260135, 2023). "Correlation between CXCL12 expression and CXCR4 (inferred via CXCL12 expression) is known to aggravate the tumor growth via ERK pathway activation." (PMID 37970206, 2023). "In turn, tumor cells secrete numerous factors such as transforming growth factor-β (TGF-β), epidermal growth factor (EGF) and C-X-C motif chemokine ligand 12 (CXCL12), which can activate and educate CAFs." (PMID 36717783, 2023). "ELISA measurements in B7H4 staining positive tumours: IL-9, IL-18, IP-10(CXCL10), MIG (CXCL9) and SDF-1a (CXCL12)." (PMID 36980202, 2023). "Several cytokines and growth factors expressed by our AFs, such as CXCL-12, IL6, FGFs and VEGFs, were shown to participate in CAFs/cancer cells crosstalk, and promote tumour progression." (PMID 37938546, 2023). "The CXCL12/CXCR4 axis plays a pivotal role in tumor development, survival, angiogenesis, metastasis, and tumor microenvironment." (PMID 37511481, 2023). "Of interest, a mouse model of CRC animal treated with neutralizing antibodies against CXCL12 and CSF1 showed a strong increase in CD8+ T lymphocyte infiltration and reduction in tumor growth." (PMID 37175861, 2023). "Tumor cells secrete chemokines (CCL2, CCL7, and CXCL12) and cytokines (VEGF) to recruit peripheral blood monocytes into tumor tissues and induce them to differentiate into TAMs." (PMID 37064113, 2023). "The CXCL12/CXCR4 axis activates multiple pathways involved in angiogenesis, metastasis, and survival in the tumor microenvironment and promotes tumor cell invasion and metastasis." (PMID 37311820, 2023). "Previous research found that the proliferation and metastasis of BC are linked to several signalling pathways, and that specific cytokines in the tumour microenvironment (TME), such as CXCR4 and CXCL12, play an important role in BC metastasis." (PMID 37162544, 2023). "CD26+ NFs enhanced tumor cell invasion via MMP-activity and recruited monocytes in a CXCL12-dependent manner, indicating that the CAFs derived from CD26+ NFs have a pro-tumorigenic phenotype." (PMID 36635273, 2023). "Activation of the CXCL12/CXCR4 axis in the TME, thus, provides paracrine signaling that mediates integrin β1 clustering on the surface of tumor cells, promoting tumor EMT." (PMID 37371856, 2023).
tumor (continued). "CAFs regulate tumor growth, metastasis, and angiogenesis by the secretion of transforming growth factor-β (TGF-β), IL-6, CXCL12, and chitinase-3-like-1 (CHI3L1)." (PMID 37108109, 2023). "ECs are one of the vital parts of TME that orchestrate with other cells to provide tumor progression, which can be recruited to the niche of the tumor upon the section of VEGF, HIF-1, and SDF-1/CXCL12 by CSCs to initiate the process of angiogenesis." (PMID 37328876, 2023). "CSCs, besides their capability to differentiate to ECs, by secretion of factors such as VEGF, HIF-1α, and CXCL12, can promote the recruitment and migration of ECs and mesenchymal stem cells (MSC) to the niche of tumor and differentiation of them into ECs." (PMID 37328876, 2023). "Surprisingly, 1,25(OH)2D also inhibited C-X-C motif chemokine Ligand 12 (CXCL12) expression, which is a key pre-metastatic niche factor that recruits tumor cells (i.e., oncogenic “seeds”), thus escalating tumor progression and metastatic potential." (PMID 37228489, 2023). "It is also known that PI3K-AKT-mTOR signaling pathway activation via CAF-derived secretion, such as through CXCL12, VCAM1, IL-22, CXCL5, HGF, and SPARC, induces tumor proliferation, migration, and stemness." (PMID 37264057, 2023). "In mouse models, interfering with the CXCR4–CXCL12 axis promoted CD8+ T cell infiltration and reduced CXCL12-mediated migration of lymphocytes and MDSCs to the TME, as well as inhibited tumor revascularization following anti-angiogenic therapy." (PMID 37190141, 2023). "Polarization of M2 phenotype to M1 phenotype is promoted when CXCL12 and CXCR4 expression is downregulated in tumor cells." (PMID 36173487, 2023). "Other ligands, such as CXCL12 and MMP9, have documented roles in invasion in other tumor types, but their role in PDAC invasion remains to be explored in depth." (PMID 36881486, 2023). "This suggests that if a GBM tumor is in a zone in which IFF is ∼ 0.5 μL/min, the initial CXCL12 dose loaded should be increased." (PMID 40838055, 2023). "Chemokines produced by tumor cells, immune cells, and tumor stromal cells, including CC­chemokine ligand 2 (CCL2), CCL5, CXC­chemokine ligand 12 (CXCL12, also known as SDF1) and CXCL1, are involved in this process." (PMID 36824409, 2023). "In a preclinical mouse model of PDAC, it was demonstrated that CAFs that express the fibroblast activation protein (FAP) within the ECM produce and secrete CXCL12, which in turn binds to the PDAC tumor cells, coating them." (PMID 37284199, 2023). "The following mechanism was: cGAMP stimulated innate and adaptive immunity, changed the tumour immune milieu, down-regulated the expression of M2-TAM and TGF-β and impaired the combining capacity of CXCR4 and CXCL12." (PMID 37162544, 2023). "CXCL12 not only binds to CXCR4, but also to CXCR3 and DPP4 on tumor cells in our study, which is consistent with previous reports." (PMID 37719863, 2023). "CAF-S1, a subset of myofibroblast, recruits CD4+CD25+ T cells to create an immunosuppressive microenvironment via CXCL12 and expresses B7H3, CD73, and DPP4 to promote their differentiation into Tregs, thereby contributing to tumor growth." (PMID 37784082, 2023). "Cytokine array analysis of CM derived from CD26− and CD26+ NFs co-cultured with tumor cells revealed that the co-culture of CD26+ NFs and tumor cells released more CXCL2 and CXCL12 than the co-culture of CD26− NFs and tumor cells." (PMID 36635273, 2023). "Being stimulated by the chemokine CXCL12, the CXCR4 / CXCR7 cascade is involved in tumor proliferation, migration, and metastasis." (PMID 37996954, 2023). "Among various flavonoids, curcumin has been extensively studied in terms of cancer therapy owing to its diverse functions, which include inhibition of the CXCL12/CXCR4 axis, resulting in suppressed tumor metastasis." (PMID 38004606, 2023). "The decoy peptide can inhibit tumor cells by targeting chemokines, such as the DV1 peptide targeting CXCL12." (PMID 37691919, 2023).
tumor (continued). "While the multiple activities orchestrated by CXCL12 in the tumor microenvironment have been well documented, as well as the presence of HMGB1, little is known on the relevance of the CXCL12/HMGB1 heterocomplex in mediating tumor growth and metastasis." (PMID 37251376, 2023). "For example, bone marrow stroma secretes C-X-C motif chemokine 12 (CXCL12), which attracts NSCLC tumor cells expressing its receptor C-X-C chemokine receptor 4 (CXCR4), directing tumor cells from blood circulation to the bone." (PMID 38002256, 2023). "Tumor cells secrete cytokines, growth factors, and chemokines such as TGF-β, CXCL12, PDGF, FGF, and IL-6 that trigger the MSCs to differentiate into CAFs." (PMID 37626931, 2023). "As stated, CCL2, CXCL12, IL-15, CD20, and CD70 are immune-related genes that have a certain significance for tumor development and immunotherapy." (PMID 37494663, 2023). "TNFα production in OC leads to increases in IL6, VEGF, C-C motif ligand 2 (CCL2), and C-X-C motif chemokine ligand 12 (CXCL12), and lower levels of TNF-α lead to a reduction in tumor growth." (PMID 37445860, 2023). "CXCL12, which is involved in CXCR4-mediated recruitment of CD8+ T cell recruitment to the tumor microenvironment, was upregulated by ionizing radiation in MOC2 cells but not in LY2, SCC83, and CAL27 HNSCC cells." (PMID 37444444, 2023). "It has been also shown that MSCs release large amounts of CXCL12 (SDF-1), which control the invasion and migration of tumor cells that express CXCR4." (PMID 36829187, 2023). "Tumor cells also release many cytokines including CCL2, CXCL12 and CSF1 that attract TAMs to help tumor escape by producing IL-10 and also directly inhibiting CAR T-cells via PD-1-PD-L1 interaction." (PMID 36569859, 2022). "CAFs also produce CCL2, CXCL12, IL-6, IL-10, glycoprotein CHI3L1, macrophage colony-stimulating factor to promote the migration of monocytes into tumor tissue and support their transdifferentiation into the M2 phenotype." (PMID 36324128, 2022). "In this context, tumour-derived factors such as stem cell factor (SCF) (considered the main survival factor for MCs), CXCL12, and CCL15 are involved in MCs recruitment." (PMID 35406451, 2022). "Moreover, since CXCL12 has several functions promoting tumor growth and metastasis besides its pro-angiogenic role, it is possible that inhibiting CXCL12 comes with secondary benefits for tumor reduction beyond angiogenesis reduction, and may serve as a better target." (PMID 35155581, 2022). "The present experiments were performed with the human tumor cell lines, A549, DLD-1, and MDA-MB- 231, which we previously characterized for expression as well as their use of CXCR4, CXCR3, and CXCR7 in CXCL12- and CXCL11-dependent chemotaxis." (PMID 36539774, 2022). "CXCL12, which was reported to induce EGFR-TKI resistance through CXCR7 in tumor cells through the ERK pathway, was decreased after EGFR-TKI treatment in our study." (PMID 36612121, 2022). "In studies of tumor angiogenesis in colorectal cancer, CXCL11 and CXCL12 have been shown to have a reciprocal regulatory role." (PMID 35770088, 2022). "Together, these findings oppose a crucial role of MMP-9 and MMP-2 in the observed combined effects of CXCL12 and CXCL11 on tumor cell invasion." (PMID 36539774, 2022). "In all tumor cells, levels of pro MMP-9 and pro MMP-2 remained unchanged following treatment with either CXCL12 or CXCL11 alone (100 ng/ml, 24 h) or in combination." (PMID 36539774, 2022). "ING5 suppresses proliferation, migration, invasion and tumor growth of various cancer cells via the suppression of EGFR/PI3K/Akt, IL-6/STAT3, Akt/NF-κB/NF-κB/MMP-9 or IL-6/CXCL12 pathway." (PMID 36425530, 2022). "Consistently, treatment with a chemical inhibitor of S100A9 or CXCL12 also significantly inhibited MDSC accumulation and slowed down tumor growth." (PMID 35304461, 2022).
tumor (continued). "CAFs’ secrete cytokines or chemokines to interfere with tumor-retarding T cells functions, such as PGE2, indoleamine 2,3-dioxygenase, CXCL12, and IL-6." (PMID 35327514, 2022). "CXCR4 is a seven transmembrane G protein-coupled receptor for CXCL12 (also called SDF-1) and a central receptor in tumor biology, and its expression controls proliferation and tumor cell survival in various tumor types." (PMID 35941537, 2022). "The tumor-promoting effects of CAFs, which exhibit a SASP phenotype similar to senescent fibroblasts, have been attributed primarily to CXCL12, which is also an important SASP component that is expressed and secreted by CAFs." (PMID 35742971, 2022). "After being stimulated by hypoxia-inducible factor (HIF-1α), TAMs release a set of angiogenic cytokines, such as vascular endothelial growth factors (VEGF)-A, TGF-β, CXCL12, PDGF, and MMPs, which in turn promote tumor angiogenesis." (PMID 36311793, 2022). "CXCL12/CXCR4 signaling promotes an immunosuppressive environment, ECM remodeling, reprogramming of tumor cells, tumor angiogenesis, and metastasis." (PMID 35155581, 2022). "On the other hand, myeloid derived suppressor cells are recruited by CCL-2, CXCL-5, CXCL-8 and CXCL-12 into the TME, building a tumor-promoting and immune-suppressive microenvironment." (PMID 36611932, 2022). "They associated the increased survival following OVV-CXCR4-A-mFc treatment with a reduction of CXCL12 and VEGF as well as cancer-initiating, endothelial, myeloid and plasmacytoid dendritic cells in the tumor microenvironment." (PMID 35155581, 2022). "Tumor samples expressed VECF-C, -D and -R3, as well as CXCL12, CCL21 and CXCR4 with the highest lymphatic vessel density at the invasive tumor edges." (PMID 35163401, 2022). "Our results suggest iCAFs as the main cell type expressing IL6, CXCL12, and LIF in the tumor milieu, wherein these ligands promote immunosuppressive changes, such as macrophage polarization, toward the M2 phenotype." (PMID 35196078, 2022). "For example, TNF-α, IL-6, IL-8, and IL-23 mediate inflammation resulting in tumor growth, and TGF-β and CXCL12/CXCR4 mainly promote metastasis." (PMID 36237303, 2022). "CXCL12, the chemokine binding to the CXCR4, is secreted from fibroblast cells in the tumor microenvironment." (PMID 35638450, 2022). "We further conclude that CXCL12, CXCL11 alone or in combination exert anti-apoptotic effects only in distinct tumor cells." (PMID 36539774, 2022). "CXCL12, produced by FAP+CAFs in the TME binds to its receptor CXCR4, expressed by T cells, thereby trapping TIL in the tumour stroma and restricting their access to tumour areas containing cancer cells." (PMID 35479076, 2022). "Chemokines (CXCL12, CXCL8, CXCL5) and chemokine receptors (CXCR1/2, CCR4, CCR8) are well-known to deeply participate in the tumor development and progression in various cancers, including LUAD." (PMID 36419650, 2022). "Increased intratumoral CXCL12 is also believed to help recruit T-cells to the TME and improve local control of tumor cells." (PMID 36358665, 2022). "CXCL12 and CXCL11 affect tumor cell functions by either binding their prime receptors, CXCR4 and CXCR3, respectively, and/or CXCR7 as a common second chemokine receptor." (PMID 36539774, 2022). "Specifically, CXCL12 controls tumor progression by binding to its receptors, CXCR4 and/or CXCR7, and subsequently affecting tumor cell survival, proliferation, and migration." (PMID 36539774, 2022). "Expression profiles of MIF, CXCL12, and the receptors CXCR4, CXCR2, CXCR7, CD74, and CD44 were first analyzed using an RNA sequencing (RNA-seq) dataset (GSE62564) of 498 primary NB tumor samples." (PMID 35715791, 2022). "The binding of the canonical CXCR4 ligand CXCL12 (SDF1) promotes tumour cell proliferation, survival, and metastasis, with the CXCR4+ tumour cells having a high self-renewal capacity and potent tumorigencity." (PMID 35205725, 2022).
tumor (continued). "In tumor–stromal cell interactions, CXCR4 and CXCL12 form an important signaling axis, with the interaction influencing adhesion, migration and invasion, reflecting the strong association of CXCR4 with the development of metastasis." (PMID 35406582, 2022). "The chemokine receptor system plays a relevant role in BC, where some chemokines and their cognate receptors, namely CXCL12 and its receptors CXCR4 and ACKR3 are found overexpressed and often dysregulated in both tumor and tumor microenvironment (TME) cells." (PMID 36233192, 2022). "CXCL12 and CXCR4 are independent prognostic factors for tumor differentiation, metastasis, and CRC survival." (PMID 35615089, 2022). "It has been reported that in a gastric cancer model, about 20% of CAFs in tumor sites are derived from BM-MSCs which have been recruited into the tumor microenvironment in a TGF-β and CXCL-12 dependent manner." (PMID 35251985, 2022). "In the present work, we have analyzed CXCL12 and CXCL11 for combined effects on migration, invasion, proliferation, and cytostatic-induced apoptosis of the human tumor cells, A549, A767, A772, DLD-1, and MDA-MB-231." (PMID 36539774, 2022). "The few available studies so far demonstrated that a combination of CXCL12 and CXCL11 either potentiated or diminished tumor cell migration when compared to single chemokines." (PMID 36539774, 2022). "The recruitment of MDSCs to the tumor microenvironment is mediated by hypoxia-dependent upregulation of stromal-derived factor 1 (SDF1, CXCL12)." (PMID 35795658, 2022). "C-X-C motif chemokine ligand 12 (CXCL12) and its receptor C-X-C motif chemokine receptor 4 (CXCR4) have emerged as promising therapeutic approaches targeting tumor growth and metastasis." (PMID 35615089, 2022). "Acid sinomenine interferes with tumor-derived DNA and affects ERK/MMP signaling via the CXCL12/CXCR4 axis in HCC cells." (PMID 35860597, 2022). "As revealed by WB analyses, the expression of CXCL12, CXCR4, CCL21, and CCR7 proteins in SK-Hep1 cells was significantly increased after transfection with tumor-derived DNA in contrast to the blank control group." (PMID 35860597, 2022). "Together, the synergic effects of the hub genes, CCL19, CXCL12, and C5AR1, promote chemotaxis, tumour proliferation, and even metastasis, which are in line with previous studies and evidenced by the progressive MCTVT growth." (PMID 34980125, 2022). "CXCL12 is released from stromal cells within the TME and thus binds to CXCR4 on the surface of tumor cells, eventually promoting tumor metastases and unfavorable survival outcomes." (PMID 35795038, 2022). "Direct contact between MM cells and CAFs through CXCL12/CXCR4 and other integrins is necessary to facilitate the tumor-promoting functions of CAFs." (PMID 36421358, 2022). "In contrast to the controls, the protein expressions of CXCR4, CXCL12, CCR7, CCL21, P-ERK1/2, MMP-9, and MMP-2 in SK-Hep1 cells were significantly increased after transfection of tumor-derived DNA, while the increase was reversed by sinobine hydrochloride." (PMID 35860597, 2022). "In turn, CXCL12 presentation in the TME and its resulting concentration gradients attract circulating CXCR4/CXCR7+ EPCs and promote tumor re-vascularization." (PMID 36568151, 2022). "The correlation between CXCL12 and CXCR7 in tumors was analyzed by fluorescence ratio (SERUM GL/tumor FL)." (PMID 36101803, 2022). "CAFs secrete growth factors (HGF, IGF1), tumour-promoting ligands (TFG-β, IL-6 and LIF) and immunosuppressive ligands (CXCL12 and CCL2)." (PMID 35072206, 2022). "In cancer, the CXCL12/CXCR4 biological axis can stimulate the proliferation and metastasis of tumor cells, regulate the inflammatory state of tumors, and activate the immune response within tumors by both autocrine and paracrine factors." (PMID 35893797, 2022). "The interaction between CXC chemokine ligand 12/chemokine stromal cell-derived factor-1 (CXCL12/SDF-1) and the corresponding receptor CXCR4 promotes tumor metastasis." (PMID 35630915, 2022).